DMD (dystrophin)
Diseases named in the same sentence as DMD in open-access papers (continued):
Sharing a sentence is not in itself a finding about the gene and the disease.
Duchenne muscular dystrophy (continued). "Duchenne muscular dystrophy (DMD) is the most common, lethal X-linked neuromuscular disorder of childhood and is caused by mutations in the Dmd gene that disrupt dystrophin expression." (PMID 42146625, 2026). "We were able to access this information in the company submissions for two NICE Highly Specialised Technology appraisals: ataluren for treating Duchenne muscular dystrophy (DMD) with a nonsense mutation in the dystrophin gene and onasemnogene abeparvovec for treating spinal muscular atrophy (SMA)." (PMID 41175292, 2026). "Rarely, CGD can be caused by a deletion in the X chromosome with larger deletions involving neighboring genes, including DMD (Duchenne muscular dystrophy) and XK (McLeod Syndrome)." (PMID 40745660, 2025). "Duchenne muscular dystrophy (DMD), the most common muscular dystrophy affects 1 : 7250 males aged 5–24 years, is an X‐linked recessive disease where dystrophin gene mutations result in sarcolemma instability and progressive muscle damage and weakness." (PMID 39923120, 2025). "In the Duchenne muscular dystrophy models, reintroducing dystrophin via gene editing improved muscle strength and function." (PMID 40465697, 2025). "In the context of Duchenne muscular dystrophy, such innovations hold the promise of achieving safer and more effective restoration of dystrophin expression through optimized and clinically viable delivery strategies." (PMID 41614822, 2025). "By revealing the molecular complexities related to dystrophin, this review paves the way for future investigations and therapeutic interventions for this CNS aspect of Duchenne muscular dystrophy." (PMID 39673425, 2025). "Clinical trials using gene-edited MSCs to express dystrophin in Duchenne muscular dystrophy have shown promise." (PMID 40809065, 2025). "Duchenne muscular dystrophy (DMD), a severe muscle disease caused by mutations in the gene encoding for the intracellular protein dystrophin, is associated with impaired cardiac function and arrhythmias." (PMID 40089543, 2025). "Duchenne muscular dystrophy (DMD) is a severe, state X-linked neuromuscular disorder caused by mutations in the dystrophin gene." (PMID 40474208, 2025). "Dystrophinopathies, including Duchenne muscular dystrophy (DMD) and Becker MD, are progressive X-linked neuromuscular disorders caused by pathogenic variants in the dystrophin gene, impacting the maintenance of the cardiac and pulmonary muscle cell membrane." (PMID 40080633, 2025). "Duchenne muscular dystrophy (DMD) is an X-linked recessive neuromuscular disorder manifested by the absence or deficiency of functional dystrophin protein in muscle resulting in chronic inflammation, replacement of muscle with fibrotic and fatty tissue and resulting muscle weakness." (PMID 39775224, 2025). "Duchenne muscular dystrophy (DMD) is a genetic neuromuscular disorder inherited in an x-linked recessive manner and caused by mutations in the dystrophin gene." (PMID 39715964, 2025). "Duchenne muscular dystrophy (DMD), a progressive pediatric neuromuscular disorder caused by loss of function mutations to the X-linked dystrophin gene, is characterized by delays in motor development, excessive muscle weakness, impaired ambulation, and eventual cardio-respiratory failure." (PMID 40542412, 2025). "Duchenne muscular dystrophy (DMD) is a recessive X-linked neuromuscular disorder with an estimated incidence of 1 in 3500 – 5000, caused by mutations in the dystrophin gene." (PMID 41427054, 2025). "Duchenne muscular dystrophy (DMD) is a rare, progressive neuromuscular disease resulting from DMD variants, leading to loss of functional dystrophin." (PMID 41104521, 2025). "In 1995, my colleagues and I proposed a splice-switching therapy for Duchenne muscular dystrophy (DMD) by inducing exon skipping of dystrophin genes with an AS-oligo." (PMID 40076889, 2025).
Duchenne muscular dystrophy (continued). "Restoration of the dystrophin protein in Duchenne muscular dystrophy patient-derived iPSCs and Atp1a3 in an alternating hemiplegia of childhood (AHC) mouse model are additional examples." (PMID 41394966, 2025). "So far, attention has been focused on the role of dystrophin in muscle, in view of the devastating progression of weakness and early death that characterizes Duchenne muscular dystrophy." (PMID 39673425, 2025). "Duchenne muscular dystrophy (DMD) mainly affects young boys with out-of-frame mutations in the DMD gene, leading to dystrophin deficiency." (PMID 40490752, 2025). "Duchenne muscular dystrophy (DMD) is the most prevalent genetic muscular disorder, arising from genetic frame‐shift mutations in the dystrophin gene, which is the largest gene in the human genome." (PMID 39949979, 2025). "Among them, Duchenne muscular dystrophy (DMD) is one of the most severe and prevalent forms, caused by mutations in the dystrophin gene." (PMID 40695994, 2025). "Duchenne muscular dystrophy (DMD), which results from mutations that disrupt the expression of dystrophin proteins, is characterized by progressive muscle fiber wasting and the development of skeletal muscle fibrosis." (PMID 41283440, 2025). "A significant increase in efficiency was observed with the failed clinical candidate drisapersen, a 2′OMe-PS SSO that promotes dystrophin exon 51 exclusion as a treatment for Duchenne muscular dystrophy." (PMID 39926316, 2025). "ASOs that modulate exon splicing of the dystrophin (DMD) gene can reduce muscle degeneration in Duchenne's muscular dystrophy." (PMID 40268518, 2025). "This is perhaps best exemplified in the case of Duchenne muscular dystrophy (DMD) patients for whom a genetic mutation in an essential structural element of muscle, DYSTROPHIN, leads to continuous destabilization of muscle fiber sarcolemma and repetitive injury." (PMID 39900735, 2025). "Duchenne Muscular Dystrophy (DMD), an X-linked recessive neuromuscular disorder due to the absence or deficiency of dystrophin protein, has a global incidence of 1 in 5000 live male births." (PMID 39080230, 2025). "Despite scientific efforts, there is no cure for Duchenne muscular dystrophy (DMD), a lethal, progressive, X-linked genetic disorder caused by mutations in the dystrophin gene." (PMID 39335509, 2024). "Duchenne muscular dystrophy (DMD) is a genetic disorder in which the protein dystrophin loses functionality and cannot distribute contractile forces, resulting in recurring sarcolemma microlesions." (PMID 39519374, 2024). "Duchenne's muscular dystrophy (DMD) is a devastating and progressive neuromuscular disorder caused by mutations in the dystrophin gene (Xp21.2)." (PMID 39583121, 2024). "Dystrophinopathies, a collective term for Duchenne muscular dystrophy (DMD), Becker muscular dystrophy (BMD), and X-linked dilated cardiomyopathy, are caused by pathogenic variants in the dystrophin-encoding DMD gene." (PMID 38486238, 2024). "Similar observations have been made in previous ASO screens for exon skipping therapies, such as DMD for Duchenne muscular dystrophy and SCN1A for Dravet syndrome." (PMID 38714659, 2024). "Duchenne muscular dystrophy (DMD) is caused by mutations in the DMD gene, resulting in the loss of dystrophin, a large cytosolic protein that links the cytoskeleton to extracellular matrix receptors in skeletal muscle." (PMID 38721692, 2024). "Duchenne muscular dystrophy (DMD) is an X‐linked lethal disease, presenting a significant challenge in medical science due to the mutations in the dystrophin gene, leading to progressive muscle degeneration, weakness and premature death." (PMID 39017908, 2024). "Duchenne muscular dystrophy (DMD) is a severe genetic disorder characterized by progressive muscle degeneration, with respiratory and cardiac complications, caused by mutations in the DMD gene, encoding the protein dystrophin." (PMID 38596212, 2024).
Duchenne muscular dystrophy (continued). "DMD gene replacement significantly improves cardiac function in a mouse model of Duchenne muscular dystrophy." (PMID 39857372, 2024). "The authors present DMD-edited microminipigs showing severe Duchenne muscular dystrophy symptoms; their human-like physiology and small size make them ideal for developing new treatments." (PMID 38702481, 2024). "For example, the DMD gene variants c.7354G>T, c.7993A>G, and c.5190G>C, which we found in the MLPA-negative DMD group, have been reported in patients with Duchenne muscular dystrophy." (PMID 38818036, 2024). "Duchenne muscular dystrophy (DMD) is characterized by the degeneration of cardiac and skeletal muscles and results from mutations in the X-linked dystrophin gene (DMD)." (PMID 39039289, 2024). "Duchenne muscular dystrophy (DMD; MIM number 310200) is an X-linked recessive condition with a high incidence of new mutations, mostly out-of-frame deletions in the dystrophin gene." (PMID 39588385, 2024). "Base editing and prime editing have shown effective and precise repair of Duchenne muscular dystrophy (DMD) gene mutations in mouse models, leading to the restoration of dystrophin expression and subsequent improvement in symptoms." (PMID 39707395, 2024). "Duchenne muscular dystrophy (DMD) arises from alterations or losses in the extensive dystrophin gene, which plays a vital role in maintaining the stability of muscle fiber cell membranes." (PMID 39684857, 2024). "Duchennes muscular dystrophy (DMD) is a severe and common muscle disease characterized by X-linked mutations in the dystrophin gene." (PMID 38705887, 2024). "These transgene free derived iMPCs successfully engrafted and restored dystrophin expression in DMD (Duchenne muscular dystrophy) mice." (PMID 38371924, 2024). "We present a case of a male patient and his younger brother with a maternally inherited inverted insertion of approximately 306 kb of chromosome 10 in the deep intronic region between exons 44 and 45 of the DMD gene, leading to Duchenne muscular dystrophy." (PMID 39595988, 2024). "Thirty-six years after the cloning of the dystrophin gene, Duchenne Muscular Dystrophy still lacks an efficacious therapy." (PMID 38438561, 2024). "Duchenne muscular dystrophy (DMD), OMIM #310,200 and Becker muscular dystrophy (BMD), OMIM #300,376 are X-linked recessive disorders caused by pathogenic variations in the DMD gene (OMIM *300,377, HGNC ID: 29)." (PMID 38195599, 2024). "A previous study of DMD, which encodes dystrophin, has shown truncated proteins could rescue the Duchenne muscular dystrophy disease phenotypes if they escape NMD; this could be an interesting avenue to explore in CLN3 disease." (PMID 39367445, 2024). "Eteplirsen alters the splicing of the Duchenne muscular dystrophy pre-mRNA by hybridizing to exon 51 of the DMD gene, which leads to the correction of the translational reading frame and the production of shortened but functional dystrophin proteins." (PMID 38534656, 2024). "Duchenne muscular dystrophy (DMD), caused by loss-of-function mutations in the dystrophin gene, results in progressive muscle weakness and early fatality." (PMID 38762116, 2024). "Duchenne muscular dystrophy (DMD), which is caused by mutation of DMD gene encoding dystrophin, is an X-linked disease with poor clinical outcomes." (PMID 38228650, 2024). "In fact, several studies have highlighted alterations in various calcium signalling and handling molecules such as calsequestrin‐1, sarcalumenin, myozenin‐1, annexins or dystrophin in ageing and muscle diseases for example, Duchenne muscular dystrophy." (PMID 39009419, 2024). "Therapeutically competent mouse muscle stem cells generated in rats restore dystrophin expression in a mouse model of Duchenne muscular dystrophy." (PMID 38713532, 2024). "Duchenne muscular dystrophy (DMD) is a degenerative muscle disease triggered by DMD gene mutations, causing dystrophin protein loss." (PMID 39156766, 2024).
Duchenne muscular dystrophy (continued). "Duchenne muscular dystrophy (DMD) is a genetic, progressive, neuromuscular disorder caused by mutations in the dystrophin gene, which is located on the X chromosome." (PMID 39335509, 2024). "Therapeutic effects on dystrophin expression in muscular dystrophies like Duchenne muscular dystrophy have been directly examined in skeletal muscle in various clinical trials." (PMID 38635147, 2024). "Duchenne muscular dystrophy (DMD) is a severe, X-linked recessive neuromuscular disorder caused by mutations in the dystrophin gene (DMD) that lead to dystrophin protein deficiency." (PMID 39110386, 2024). "Background/Objectives: Antisense oligonucleotide (ASO)-mediated exon-skipping is an effective approach to restore the disrupted reading frame of the dystrophin gene for the treatment of Duchenne muscular dystrophy (DMD)." (PMID 39596689, 2024). "Duchenne muscular dystrophy (DMD) is one of the most common forms of muscular dystrophies, caused by mutations in the X-linked dystrophin gene, with an estimated incidence of approximately 1 in 5000 live male births." (PMID 38762116, 2024). "For example, the dystrophin mRNA (DMD, NM_004006.3), which is mutated in Duchenne Muscular Dystrophy, has 11058 nucleotides-long coding sequence." (PMID 38499809, 2024). "The EVs derived from iPSC-derived cardiomyocytes (iCMs) have shown the ability to promote angiogenesis and enhance the expression of dystrophin for Duchenne muscular dystrophy." (PMID 38247835, 2024). "Duchenne muscular dystrophy (DMD), the most prevalent form of muscular dystrophy, is a genetic disorder stemming from mutations in the dystrophin gene." (PMID 38203802, 2024). "Heart failure contributes to Duchenne muscular dystrophy (DMD), which arises from mutations that ablate dystrophin, rendering the plasma membrane prone to disruption." (PMID 38050701, 2024). "In males, a hemizygous DMD variant may result in Duchenne muscular dystrophy (DMD), Becker muscular dystrophy (BMD), or isolated X‐linked dilated cardiomyopathy (XLDCM)." (PMID 36424846, 2023). "Duchenne muscular dystrophy (DMD) is a severe, progressive, and fatal pathology directly linked to the mutation of the dystrophin gene on the X chromosome." (PMID 37894969, 2023). "Duchenne Muscular Dystrophy (DMD) is the most prevalent of the dystrophinopathies, muscle disorders caused by pathogenic variants of the dystrophin gene." (PMID 36975851, 2023). "The X-linked muscular dystrophy (mdx) mouse is a widely used animal model for Duchenne muscular dystrophy (DMD), as it also develops an X-linked recessive inflammatory myopathy, and a deficit in the gene coding for dystrophin occurs in both." (PMID 37813938, 2023). "Mutations in the DMD gene are causative for Duchenne muscular dystrophy (DMD)." (PMID 37667454, 2023). "An endosomal escape vehicle-conjugated, splice-modulating oligonucleotide restored dystrophin protein expression in striated muscles in the mdx mouse, a model for Duchenne muscular dystrophy." (PMID 37538053, 2023). "Duchenne muscular dystrophy (DMD) is a severe, progressive muscle‐wasting disorder that results from mutations to the gene for the protein dystrophin." (PMID 37415288, 2023). "Last, transgene-free iMPCs robustly engrafted skeletal muscles of a Duchenne muscular dystrophy mouse model, restoring dystrophin expression in hundreds of myofibers." (PMID 37553383, 2023). "Duchenne muscular dystrophy (DMD) is an X-linked hereditary disease affecting approximately 1 in 5000 male births worldwide and is caused by mutations in the gene that encodes the 427-kDa cytoskeletal protein dystrophin." (PMID 37233184, 2023). "Duchenne muscular dystrophy (DMD) is a rare disease that affects 1 in 3500–7000 male births worldwide and is characterized by inflammation and progressive degeneration of the skeletal and cardiac muscles resulting from mutations in the dystrophin gene." (PMID 36869352, 2023).
Duchenne muscular dystrophy (continued). "Duchenne muscular dystrophy (DMD) is an X-linked, incurable, degenerative neuromuscular disease caused by mutations in the DMD gene coding for dystrophin protein." (PMID 37434186, 2023). "Until recently, the gold standard for prenatal diagnosis of Duchenne muscular dystrophy implied invasive tissue sampling by CVS or amniocentesis followed by PCR and Sanger sequencing and/or MLPA technique in order to identify potential DMD gene mutations." (PMID 36672993, 2023). "As a result, we detected the de novo deletion of exons 38–45 of the DMD gene, leading to a frameshift, which is characteristic of a more severe disease form: Duchenne muscular dystrophy." (PMID 37569734, 2023). "For instance, antisense oligonucleotide-induced exon-skipping enables synthesis of partially functional dystrophin in patients with Duchenne muscular dystrophy." (PMID 36902751, 2023). "For example, Duchenne muscular dystrophy (OMIM#310200), an X-linked recessive myopathy caused by a mutation in the dystrophin gene located at Xp21, has a penetration rate of 100% in males." (PMID 38201393, 2023). "Previously, we reported the construction of HAC vectors containing the entire dystrophin genomic region (DYS-HAC) for gene therapy targeting Duchenne muscular dystrophy (DMD)." (PMID 37353691, 2023). "Duchenne muscular dystrophy (DMD) is a rare, X-linked recessive muscle disorder caused by mutations in the dystrophin gene and affects roughly 1/5000 male births." (PMID 37511179, 2023). "A few studies have highlighted the potential of DG9-conjugated PMOs in DMD (Duchenne Muscular Dystrophy) and SMA (Spinal Muscular Atrophy), displaying significant exon skipping/inclusion and functional improvements in animal models." (PMID 37830609, 2023). "Due to its close association with α-syntrophin, which in turn facilitates interaction with the DAPC, several groups studied the expression patterns of α-syntrophin and AQP4 in Duchenne muscular dystrophy (DMD), which is caused by mutations in the dystrophin gene." (PMID 36675000, 2023). "Deficiencies in DMD are known to cause Duchenne muscular dystrophy, a disease found to be associated with increased intracellular Ca2+ concentrations, as the DMD protein acts as scaffolding for calcium ion channels and is therefore involved in regulating calcium ion homeostasis." (PMID 37408201, 2023). "Duchenne muscular dystrophy (DMD) and Becker muscular dystrophy (BMD) are rare neuromuscular diseases caused by a mutation in the gene that produces dystrophin, which is responsible for maintaining muscle properties." (PMID 37990809, 2023). "Exon skipping is the approach used by a series of ASO drugs to treat Duchenne muscular dystrophy (DMD), an X-linked condition where the affected gene, dystrophin (also abbreviated to DMD), has many exons (a maximum of 79) which are naturally combined in a great variety of functional splice variants." (PMID 36678889, 2023). "Duchenne muscular dystrophy (DMD) is a rare X-linked recessive degenerative muscle condition affecting 1 in 4000 male live births and caused by mutations in the dystrophin-encoding DMD gene." (PMID 37470794, 2023). "Through base editing, the expression of key proteins that are dysregulated in rare genetic forms of dilated cardiomyopathies (DCM), such as dystrophin in Duchenne muscular dystrophy and Rbm20, can be restored, representing a promising therapeutic concept." (PMID 36834573, 2023). "In one of the most devastating muscle-wasting diseases, Duchenne muscular dystrophy (DMD), SCs deficient in dystrophin lose polarity and are unable to appropriately form a niche, leading to a dysfunctional progenitor state, failed regeneration, and/or disease exacerbation." (PMID 35934562, 2023). "Duchenne muscular dystrophy (DMD) is a rare, progressive, X-linked neuromuscular disease caused by the absence of functional dystrophin protein in skeletal, cardiac, and respiratory muscle due to mutations in the DMD gene." (PMID 37497476, 2023).